PGM3 (phosphoglucomutase 3)
Description:
Catalyzes the conversion of GlcNAc-6-P into GlcNAc-1-P during the synthesis of uridine diphosphate/UDP-GlcNAc, a sugar nucleotide critical to multiple glycosylation pathways including protein N- and O-glycosylation.
Synonyms: PAGM; PGM 3; AGM1; DKFZP434B187; IMD23
Tractability: PROTAC: ubiquitination databases record sites on it; its protein half-life has been measured.
Gene: Protein-coding gene on chromosome 6 (83,147,324 to 83,194,005, reverse strand). Ensembl gene ENSG00000013375.
Subcellular location (Human Protein Atlas): Cytosol; Nucleoplasm
Pathways (Reactome):
Metabolism of proteins: Synthesis of UDP-N-acetyl-glucosamine
Gene Ontology:
Molecular function: phosphoacetylglucosamine mutase activity; intramolecular phosphotransferase activity; magnesium ion binding
Biological process: protein N-linked glycosylation; protein O-linked glycosylation; UDP-N-acetylglucosamine biosynthetic process; glucosamine metabolic process; hemopoiesis; carbohydrate metabolic process
Cellular component: cytosol
Genetic constraint (gnomAD): Loss-of-function variants: 29 observed, 41.08 expected, observed/expected ratio (o/e) 0.71, 90% interval 0.52 to 0.96. The upper end of that interval is the gene's LOEUF score, 0.96, which puts it in group 4 of 6, group 1 being the genes least tolerant of losing a copy. Missense variants: 343 observed, 432.79 expected, observed/expected ratio (o/e) 0.79, 90% interval 0.73 to 0.87. Synonymous variants: 129 observed, 154.91 expected, observed/expected ratio (o/e) 0.83, 90% interval 0.72 to 0.96.
Gene-disease validity (ClinGen):
ClinGen rates the evidence that PGM3 causes each of these diseases.
immunodeficiency 23 (autosomal recessive): Definitive.
Homologues: Orthologues: chimpanzee PGM3 (99% identical), macaque PGM3 (99% identical), dog PGM3 (92% identical), guinea pig PGM3 (90% identical), rabbit PGM3 (90% identical), pig PGM3 (88% identical), mouse Pgm3 (88% identical), rat Pgm3 (83% identical), tropical clawed frog pgm3 (70% identical), zebrafish pgm3 (68% identical), Drosophila melanogaster nst (53% identical), Caenorhabditis elegans pgm-3 (41% identical). Paralogues in human: PGM2 (20% identical), PGM2L1 (19% identical), PGM1 (15% identical), PGM5 (12% identical), HPRT1 (6% identical), PRTFDC1 (5% identical).
Diseases named in the same sentence as PGM3 in open-access papers:
PGM3 is named in the same sentence as 93 diseases in open-access papers, as found by Europe PMC text mining. Sharing a sentence is not in itself a finding about the gene and the disease. The quoted sentences say what the papers report.
Immunodeficiency (16 papers, 2018 to 2025). Failure of the immune system to protect the body adequately from infection, due to the absence or insufficiency of some component process or substance. "In fact, phosphoglucomutase 3 (PGM3) deficiency induces an AR disease with immunodeficiency and tendency to bone marrow failure, severe atopy, severe skeletal dysplasia, and neurodevelopmental delay." (PMID 39945219, 2025). "Hypomorphic mutations in the phosphoacetylglucosamine mutase 3 (PGM3) gene cause a glycosylation disorder that leads to immunodeficiency." (PMID 39776909, 2024). "Phosphoglucomutase 3 (PGM3)-CDG is a congenital disorder of glycosilation associated with immunodeficiency and consequent recurrent bacterial and fungal infections, often characterized by increased levels of IgE." (PMID 37894204, 2023). "PGM3 deficiency, a rare autosomal recessive congenital glycosylation disorder, is a subtype of the severe immunodeficiency caused by variants in PGM3." (PMID 38137719, 2023). "Mutations in PGM3 are found in combined immunodeficiency disorders, which underscores the importance of the HBP for a functional immune system (see Section 5.6)." (PMID 37107691, 2023). "In humans, mutations of PGM3 occur in severe immunodeficiencies that are characterized by T and B cell dysfunctions." (PMID 37107691, 2023). "PGM3 deficiency has variable clinical features ranging from the phenotype of STAT3 deficiency to severe combined immune deficiency (SCID)." (PMID 36140582, 2022). "Previous studies have demonstrated that PGM3 mutations were associated with severe immunodeficiency and glycosylation disorder, commonly accompanied by neurodevelopmental disorders and occasionally by seizures." (PMID 33193641, 2020). "Studies on PGM3 mutants demonstrate immune deficiency, decreased cytokine production, and increased susceptibility to avian influenza." (PMID 30486457, 2018). "A novel immunodeficiency, frequently accompanied by high serum-IgE, and caused by mutations in the PGM3 gene was described in 2014." (PMID 30157810, 2018). "We found that PGM3 deficiency, a subtype of severe immunodeficiency, predisposes patients to MDS." (PMID 38137719, 2023). "In addition, this case further increases the clinical phenotypes of immunodeficiency caused by PGM3 mutations." (PMID 30157810, 2018). "PGM3 deficiency presents with a broad phenotypic spectrum, ranging from SCID-like immunodeficiency to milder HIES-like syndromes." (PMID 40698220, 2025). "EXTL3- and PGM3-CDG are the CDG included in the category of combined immunodeficiencies with syndromic features, presenting variable immunophenotypes ranging from isolated infections to severe immunodeficiency, including neurodevelopmental and skeletal defects." (PMID 38550576, 2024). "In conclusion, we identified four novel heterozygous PGM3 mutations in patients with IFE without apparent manifestation of immunodeficiency and glycosylation disorder." (PMID 33193641, 2020). "There is still no specific phenotype identified that distinguishes immunodeficiency caused by PGM3 mutations from other forms of immunodeficiency." (PMID 30157810, 2018). "Biallelic hypomorphic PGM3 mutations cause a rare autosomal recessive congenital disorder of glycosylation with a spectrum of clinical phenotypes, including T-B-NK + severe combined immunodeficiency with or without syndromic features, combined immunodeficiency, or primary atopic disorder (PAD)." (PMID 41608055, 2025). "In this study, four novel heterozygous PGM3 variants, including two de novo variants, were identified in the cases with IFE and without the manifestation of immunodeficiency or glycosylation disorders." (PMID 33193641, 2020).
breast carcinoma (9 papers, 2018 to 2025). "Building on previous reports demonstrating the antitumor efficacy of FR054—a competitive inhibitor of PGM3—in breast cancer, pancreatic cancer, and pancreatic ductal adenocarcinoma—we extended these findings to GBM." (PMID 40772310, 2025). "Targeting of PGM3 inhibits the hexosamine synthetic pathway and has been found to result in growth arrest and apoptosis in breast cancer cells." (PMID 35614441, 2022). "It has been reported that PGM3 suppression in breast cancer cells leads to cell death through the induction of endoplasmic reticulum (ER) stress and reactive oxygen species (ROS)." (PMID 35011738, 2022). "As another ascending pattern gene, PGM3 is one of the hexosamine biosynthetic pathway enzymes that reveal a critical role in tumor progression in breast cancer." (PMID 35031021, 2022). "Here we report the preclinical evaluation of FR054, a novel inhibitor of the HBP enzyme PGM3, with a remarkable anti-breast cancer effect." (PMID 29515119, 2018). "FR054, a competitive inhibitor of PGM3, was initially developed for breast cancer therapy." (PMID 40772310, 2025). "High levels of PGM3 mRNA correlate with poor prognosis in not only NSCLC and breast cancer but also bladder cancer in a human cohort, suggesting that FR054 treatment may have therapeutic potential for a broader range of tumor types." (PMID 35011738, 2022). "Our findings may suggest a more general relationship of ANA with anti-PGM3 TAA regardless of breast cancer, which could have implications for use of this antigen as a potential cancer biomarker." (PMID 38002248, 2023). "Of note, an inhibitor targeting PGM3, which converts GlcNAc-6-P to GlcNAc-1-P and is thus required for both de novo UDP-GlcNAc synthesis and GlcNAc recycling, showed efficacy in treating gemcitabine-resistant patient-derived xenograft PDA models, as well as in breast cancer xenografts." (PMID 34844667, 2021). "Although the up/down-regulation reports in breast cancer on SF3B3 and PGM3 corroborate our findings, there is no report concerning the ascending trend of these genes across stages." (PMID 35031021, 2022).
pancreatic cancer (8 papers, 2016 to 2025). "PGM3 is also overexpressed in human pancreatic cancer tissues, and its upregulation is associated with poorer median overall survival." (PMID 37107691, 2023). "Upon increasing GEM doses, PGM3 and global protein O-GlcNAcylation levels are decreased in sensitive BxPC-3 pancreatic cancer cells but increased in PANC-1 and MIA PaCa-2 resistant ones." (PMID 36059648, 2022). "Numerous instances exist, such as the inhibition of phosphoglucomutase 3 (PGM3) activating UPR to counteract gemcitabine resistance in pancreatic cancer, and the activation of the IRE1–XBP1 pathway of UPR overcoming ibrutinib resistance in diffuse large B-cell lymphoma." (PMID 39080273, 2024). "Gemcitabine-resistant pancreatic cancer has upregulated PGM3." (PMID 37107691, 2023). "In a study on pancreatic cancer, the upregulation of PGM3 correlated significantly with gemcitabine resistance, while inhibiting PGM3 significantly suppressed the malignant phenotype of tumor cells and enhance the drug sensitivity of gemcitabine by modulating the EGFR-Akt pathway." (PMID 36275679, 2022). "Moreover, the HBP enzyme Phosphoacetylglucosamine Mutase 3 (PGM3) was shown to be overexpressed in GEM resistant human pancreatic tumors." (PMID 36059648, 2022). "Recent studies reported that FR054, a specific inhibitor of PGM3, has an anti-cancer effect in breast and pancreatic cancer models, both in vitro and in vivo without having severe adverse effects." (PMID 35011738, 2022). "Therapeutic approaches involving PGM3 inhibition, and possibly inhibition of protein O-GlcNAcylation, in combination with GEM could be promising to bypass the drug resistance in pancreatic cancer." (PMID 36059648, 2022). "PGM3 mRNA levels were found to be down-regulated in pancreatic cancer in the GSE28735 dataset, while no significant changes were observed in the other five datasets." (PMID 27996048, 2016).
neutropenia (5 papers, 2022 to 2025). A decrease in the number of neutrophils found in the blood. "Nonetheless, neutropenia is a relatively common finding in PGM3 deficiency, reported in approximately 43% of cases (16/38), and is observed across both HIES-like and CID/SCID-like phenotypes." (PMID 40698220, 2025). "In summary, although PGM3 deficiency is a multisystemic disorder, hallmark features of recurrent infections, chronic severe neutropenia, and virus-driven malignancies with early adult mortality strongly support early HSCT consideration in these patients." (PMID 41608055, 2025). "PGM3 deficiency is a multisystem disorder characterized by recurrent infections, chronic severe neutropenia, and virus-associated malignancies, often leading to premature mortality in early adulthood." (PMID 41608055, 2025). "Patients with PGM3 deficiency commonly experience neutropenia, reduced memory B-cell, and T-cells counts." (PMID 40040707, 2025). "Neutropenia has also been reported in some patients with deficiency in phosphoglucomutase 3 (PGM3), a disorder of glycosylation which is currently classified as autosomal-recessive Hyper IgE syndrome." (PMID 38720948, 2024). "PGM3 deficiency can present with lymphopenia and neutropenia." (PMID 36140582, 2022). "Neonatal-onset SCID and neutropenia were reported in patients with deleterious PGM3 mutations." (PMID 36140582, 2022). "Additionally, reports on the outcomes of HSCT in PGM3 deficiency, though limited, highlight that hematopoietic stem cell transplantation with cord blood or bone marrow from matched related donors led to successful engraftment and resolution of both neutropenia and lymphopenia." (PMID 40040707, 2025).
prostate carcinoma (5 papers, 2010 to 2022). A carcinoma that arises from epithelial cells of the prostate gland. "For example, sulforaphane can reduce PGM3 expression in prostate cancer cells by inducing apoptosis." (PMID 31582909, 2019). "We here demonstrate that phosphoglucomutase-3 (PGM3) plays a role in the regulation of SFN-induced apoptosis in LNCaP prostate cancer cells." (PMID 21159204, 2010). "Furthermore, a blockade of PGM3 expression with sulforaphane was shown to promote apoptosis in prostate cancer cells." (PMID 35614441, 2022). "In light of these events, we considered that PGM3 may play a role in the regulation of prostate cancer cell survival." (PMID 21159204, 2010). "Depletion of either UAP1 or PGM3 with two independent siRNAs significantly reduced cell viability of both LNCaP and CWR22Rv1 cells in comparison to cells treated with the control siRNA, consistent with expression of both these enzymes being important for prostate cancer cell survival." (PMID 27428423, 2016). "Though relatively fewer studies on another two HBP genes, GNPNAT1 and PGM3, the overexpression of GNPNAT1 and PGM3 was reported in lung adenocarcinoma and prostate cancer, respectively." (PMID 36158580, 2022). "Of 31 reciprocally-regulated glycosylation enzymes, a set of 8 (GALNT7, ST6GalNAc1, GCNT1, UAP1, PGM3, CSGALNACT1, ST6GAL1 and EDEM3) were significantly up-regulated in clinical prostate carcinoma." (PMID 27428423, 2016). "Taken together, these findings suggest that PGM3 plays a role in mediating SFN-induced cell death in LNCaP cells, and is a potential molecular therapeutic target for prostate cancer." (PMID 21159204, 2010). "Our findings suggest that PGM3 is involved in mediating SFN-induced cell death in LNCaP cells and may be a potential molecular target for prostate cancer therapeutics." (PMID 21159204, 2010).
Autoimmunity (4 papers, 2016 to 2025). The occurrence of an immune reaction against the organism's own cells or tissues. "Phosphoacetylglucosamine mutase (PGM3) is one of several paralogues (PGM1-3,5) that control glucose metabolism in most cells, and defects in PGM3 have been linked to autoimmunity." (PMID 38002248, 2023). "PGM3 deficiency presents with hyper-IgE–like features, atopy, autoimmunity and neurocognitive impairment." (PMID 27222657, 2016). "Indeed, the predominance of atopy and infections over autoimmunity in patients suggests complex PGM3-dependent effects in vivo." (PMID 39776909, 2024). "Autosomal recessive hypomorphic mutations in the phosphoglucomutase 3 gene PGM3 can lead to a clinical SCID phenotype with features of HIES, with elevated IgE, severe atopy, systemic bacterial infections, disseminated Herpesvirus infections, neurologic impairment, and increased autoimmunity." (PMID 41181176, 2025).
hyper-IgE syndrome (4 papers, 2018 to 2026). A condition that is characterized by elevated serum IgE, dermatitis, and respiratory infections. "These human hyper-IgE syndromes (HIES) include the autosomal dominant Job ́s syndrome and autosomal recessive PGM3 (phosphoglucomutase 3) and SPINK5 (Serine Peptidase Inhibitor Kazal Type 5) syndromes, that can be successfully treated with anti-IgE antibody therapy or stem cell transplantation." (PMID 32695309, 2020).
Netherton syndrome (4 papers, 2020 to 2025). Netherton syndrome (NS) is a skin disorder characterized by congenital ichthyosiform erythroderma (CIE), a distinctive hair shaft defect (trichorrhexis invaginata; TI) and atopic manifestations. "Atopic dermatitis (AD) is reported to be correlated with AD‐HIES (job's syndrome), IPEX, Netherton syndrome, PGM3 deficiency, DOCK8 deficiency, STAT3 GOF, Omenn syndrome, activated leukocyte cell adhesion molecule (ALCAM), and hypereosinophilia." (PMID 37102642, 2023).
atopic dermatitis (3 papers, 2016 to 2025). "Atopic dermatitis/eczema affected 24.6%, and 4.2% were explicitly labeled as atopic dermatitis (mostly among patients with Phosphoglucomutase 3 (PGM3) deficiency)." (PMID 41142799, 2025). "In this study, immunoprecipitation was used to prepare two IgE samples from less than 1 mL of sera/plasma: one was from a patient with PGM3 mutation, the other was from a patient with atopic dermatitis as a control subject." (PMID 26687240, 2016). "Consistently, two glycoproteomic studies showed similar site-specific glycan profiles of IgE protein between a PGM3 mutant patient (p.E340del) and an atopic dermatitis patient and between a healthy individual and a hyperimmune individual." (PMID 39776909, 2024). "However, our previous studies showed similar N-glycan profiling and in vivo stability of IgE proteins among samples derived from patients with elevated IgE-associated atopic dermatitis, HIES with LOF-STAT3, PGM3 insufficiency, and DOCK8 deficiency, compared to healthy individuals (unpublished data)." (PMID 39776909, 2024). "Moreover, our glycomic studies of IgE showed that the overall profile of N-glycans did not change significantly from a patient with PGM3 mutations and a patient with atopic dermatitis." (PMID 26687240, 2016).
colorectal cancer (3 papers, 2023 to 2024). A primary or metastatic malignant neoplasm that affects the colon or rectum. "For example, PGM3-mediated O‐GlcNAcylation of β-catenin enhanced β-catenin activity, thereby facilitating colorectal cancer progression." (PMID 38585626, 2024). "Similar to PGM3 in colorectal cancer, the upregulation of UAP1 in liver cancer correlates with increased O-GlcNAcylation and overexpression of β-catenin." (PMID 37107691, 2023). "Furthermore, PGM3 is upregulated in colorectal cancer tissues, where it maintains β-catenin activity by elevating protein O-GlcNAcylation." (PMID 37107691, 2023). "This regulation of β-catenin by O-GlcNAc is mediated by phosphoglucomutase 3 (PGM3), which is highly expressed in colorectal cancer and is sufficient to elevate total level of O-GlcNAc in colorectal cancer cells." (PMID 37838167, 2023).
eczema (3 papers, 2018 to 2025). "Other recessive mutations, such as those in the TYK2 and PGM3 genes, have been associated with hyper-IgE syndrome, as have other genetic anomalies leading to hyper IgE, eczema, and dysimmune manifestations." (PMID 38983983, 2024).
glycosylation disorder (3 papers, 2016 to 2024). "Congenital deficiency of both PGM-1 and PGM-3 are associated with glycosylation disorders." (PMID 27707936, 2016).
Omenn syndrome (3 papers, 2017 to 2025). An inflammatory condition characterized by erythroderma, desquamation, alopecia, chronic diarrhea, failure to thrive, lymphadenopathy, and hepatosplenomegaly, associated with severe combined immunodeficiency (SCID). "Consanguinity rate was particularly high in patients with Omenn syndrome (88.8%), phosphoglucomutase 3 (PGM3) deficiency (85.7%), leukocyte adhesion deficiency type 1 (LAD I) (76.4%), and MHC class II deficiency (70.3%)." (PMID 28702026, 2017).
primary immunodeficiencies (3 papers, 2018 to 2025). "The prevalence of germline predisposition to myeloid neoplasm in young-onset MDS was approximately 16%, largely associated with primary immunodeficiencies, and we have demonstrated the PGM3 variants as the cause of germline predisposition for the first time." (PMID 38137719, 2023). "A newly identified gene causing primary immunodeficiency is PGM3 that encodes phosphoglucomutase 3 (PGM3)." (PMID 30157810, 2018). "Genetic analysis using a next-generation sequencing panel for primary immunodeficiencies identified compound heterozygous likely pathogenic variants in PGM3: a missense variant (c.1475C>T, p.(Thr492Ile)) and a complete gene deletion in the other allele, confirming the diagnosis of PGM3 deficiency." (PMID 40698220, 2025).